TMEM141 (transmembrane protein 141)
Synonyms: MGC14141
Tractability: Antibody: UniProt predicts a signal peptide or a membrane-spanning region. PROTAC: its protein half-life has been measured.
Gene: Protein-coding gene on chromosome 9 (136,791,303 to 136,793,317, forward strand). Ensembl gene ENSG00000244187.
Subcellular location: Membrane
Subcellular location (Human Protein Atlas): Mitochondria; Cell Junctions
Gene Ontology:
Molecular function: protein binding
Cellular component: mitochondrion; membrane
Genetic constraint (gnomAD): Loss-of-function variants: 18 observed, 14.55 expected, observed/expected ratio (o/e) 1.24, 90% interval 0.85 to 1.78. The synonymous counts are far from expectation, so gnomAD's model fits this gene poorly and the ratio says little. Missense variants: 161 observed, 128.55 expected, observed/expected ratio (o/e) 1.25, 90% interval 1.1 to 1.43. Synonymous variants: 69 observed, 48.27 expected, observed/expected ratio (o/e) 1.43, 90% interval 1.18 to 1.74.
Homologues: Orthologues: chimpanzee TMEM141 (95% identical), guinea pig TMEM141 (82% identical), pig TMEM141 (81% identical), mouse Tmem141 (79% identical), rat Tmem141 (56% identical), zebrafish tmem141 (55% identical), Drosophila melanogaster CG42488 (11% identical). Paralogues in human: ODAD3 (22% identical), CCDC63 (16% identical), ODAD1 (15% identical).
Diseases named in the same sentence as TMEM141 in open-access papers:
TMEM141 is named in the same sentence as 2 diseases in open-access papers, as found by Europe PMC text mining. Sharing a sentence is not in itself a finding about the gene and the disease. The quoted sentences say what the papers report.
cancer (1 paper, 2024). A tumor composed of atypical neoplastic, often pleomorphic cells that invade other tissues. "The remaining eight target genes (CFL1, FNBP4, NDUFB3, OCIAD2, PLIN3, POU2AF1, RAC1, TMEM141) presented a combined influence in five or fewer cancer types." (PMID 39201394, 2024). "However, data regarding TMEM141’s role in cancer are scarce." (PMID 39201394, 2024).
tumour (1 paper, 2021). "We confirmed global epigenetic modification associated with reduced H4R3me2S and re-expression of tumour suppressors, such as EIF3F, FOXP4, ZBTB4, GANAB, TMEM141, in association with loss of clonogenicity." (PMID 33795785, 2021). "Overexpression of tumour suppressors, such as EIF3F, FOXP4, ZBTB4, GANAB, TMEM141 was observed." (PMID 33795785, 2021).